AFAP1-AS1 (AFAP1 antisense RNA 1)
Synonyms: ATMLP; MGC10981; AFAP1-AS; AFAP1AS
Gene: Long non-coding RNA gene on chromosome 4 (7,754,077 to 7,778,928, forward strand). Ensembl gene ENSG00000272620.
Diseases named in the same sentence as AFAP1-AS1 in open-access papers:
AFAP1-AS1 is named in the same sentence as 13 diseases in open-access papers, as found by Europe PMC text mining. Sharing a sentence is not in itself a finding about the gene and the disease. The quoted sentences say what the papers report.
lung cancer (3 papers, 2023 to 2024). A malignant neoplasm involving the lung. "Herein, it is found that lncRNA AFAP1‐AS1 encodes a conserved 90‐amino acid peptide located on mitochondria, named lncRNA AFAP1‐AS1 translated mitochondrial‐localized peptide (ATMLP), and it is not the lncRNA but the peptide that promotes the malignancy of nonsmall cell lung cancer (NSCLC)." (PMID 36871154, 2023).
non-small cell lung carcinoma (3 papers, 2023 to 2026). A group of at least three distinct histological types of lung cancer, including non-small cell squamous cell carcinoma, adenocarcinoma, and large cell carcinoma. "AFAP1 antisense RNA 1 (AFAP1-AS1) was upregulated in non-small cell lung cancer tissues and cell lines." (PMID 36765563, 2023).
colonic carcinoma (1 paper, 2016). "To investigate the function involvement of AFAP1-AS1 in hepatic metastasis of colonic carcinoma, we injected the AFAP1-AS1-specific siRNA-treated SW480 cells to spleen of nude mice for purpose of examination of number of metastasis nodules." (PMID 27578191, 2016).
ovarian carcinoma (1 paper, 2021). A malignant neoplasm originating from the surface ovarian epithelium. "Abnormally expressed in various tumors, long non-coding RNAs (lncRNAs) feature prominently in tumor development, yet little is still known regarding the functional roles of lncRNA AFAP1 antisense RNA 1 (AFAP1-AS1) in ovarian cancer (OC)." (PMID 33926489, 2021).
pancreatic ductal adenocarcinoma (1 paper, 2017). An infiltrating adenocarcinoma that arises from the epithelial cells of the pancreas. "Moreover, high AFAP1-AS1 level has also been identified as a negative prognostic factor, as it correlates with metastasis development and poorer overall survival in pancreatic ductal adenocarcinoma patients with surgical resection." (PMID 29212176, 2017).
triple-negative breast carcinoma (1 paper, 2022). An invasive breast carcinoma which is negative for expression of estrogen receptor (ER), progesterone receptor (PR), and human epidermal growth factor receptor 2 (HER2). "Lnc- AFAP1 antisense RNA 1 (AFAP1-AS1) can promote tumor progression and invasion by regulating the miR-2110/Sp1 axis in triple-negative breast cancer." (PMID 35156508, 2022).
tumor (6 papers, 2016 to 2026). "ATMLP, a mitochondrial-localized peptide encoded by lncRNA AFAP1-AS1, has been previously associated with tumor progression." (PMID 41694583, 2026). "Functional involvement of AFAP1-AS1 in tumor proliferation and metastasis was evaluated in AFAP1-AS1-specific siRNA-treated CRC cells and in CRC cell xenograft." (PMID 27578191, 2016).
AFAP1-AS1 also shares sentences with these, for which no sentence is quoted: Barrett esophagus (1 paper); breast carcinoma (1); cancer (1); esophageal adenocarcinoma (1); laryngeal carcinoma (1); retinoblastoma (1).